TNF (tumor necrosis factor)
Diseases named in the same sentence as TNF in open-access papers (continued):
Sharing a sentence is not in itself a finding about the gene and the disease.
ovarian carcinoma (continued). "Since TNF- α exerts its effects primarily via modulating the NF-κB pathway, selective inhibitors of the NF-κB pathway, e.g., Bortezomib, have been tested in prostate cancer, myeloma, and ovarian cancer." (PMID 34912809, 2021). "In addition, the use of siRNA to HVEM on ovarian cancer in vitro promoted T cell proliferation and TNF-α and IFN-γ production." (PMID 34208480, 2021). "In addition, the expression of CXCL2 has been shown to be induced by TNF-mediated signaling in ovarian cancer cells." (PMID 33807638, 2021). "Hub genes including TNF, ESR1, MUC1 and FOXO1 might be potential targets for diagnosis or treatment of ovarian cancer in an epigenetic approach, TNF, ESR1 and FOXO1 may serve as potential markers for ovarian cancer prognosis evaluation." (PMID 32192517, 2020). "In vitro cross-linking of MOv18 IgE-bound human monocytes by FRα-expressing IGROV1 ovarian carcinoma cells exhibited the same cytokine signature (TNFα, MCP-1) observed in vivo, with secretion and IGROV1 mRNA expression of MCP-1 inhibited by pretreatment with a TNFα receptor-blocking antibody." (PMID 33081206, 2020). "TNF, ESR1, MUC1 and FOXO1 are our candidate genes that might take part in ovarian cancer progression in an epigenetic approach, TNF, ESR1 and FOXO1 may serve as potential markers for ovarian cancer prognosis evaluation." (PMID 32192517, 2020). "There are significantly increased levels of Th1-polarizing chemokines and cytokines such as IL-12, IL-1Rα, TNF-α after DC vaccine treatment of ovarian cancer patients, while Th2-priming cytokines IL-4, IL-5, and IL13 are at low levels suggesting that DC vaccines elicit a Th-1 antitumor effect." (PMID 33584699, 2020). "Ovarian cancers are known to induce expression of TNFα and IL-1β." (PMID 31767036, 2019). "Finally, it works through targeting IκB kinase-beta to increase TNF-α-induced ovarian cancer cell apoptosis." (PMID 31681604, 2019). "A recent study has reported that the presence of M1 macrophage in the tumor microenvironment increases the metastatic potential of ovarian cancer cells through the activation of the nuclear factor-κB signaling pathway by releasing tumor necrosis factor alpha (TNF-α)." (PMID 31277406, 2019). "In addition, the data visualisation demonstrated that TNF response factors in ACSN are linked to the vitamin B2 metabolism in ReconMap 2.0 map and show differential regulation between the two subtypes of ovarian cancer." (PMID 30999838, 2019). "TNF-α is a cytokine that induces inflammation in ovarian cancer cells." (PMID 29844932, 2018). "Ji and colleagues showed that TAMs secreted VEGF-C following TNF-α stimulation and acted on LEC independent of VEGFR3, thereby questioning previously reported direct angiogenic and lymphangiogenic effects of TNF-α in Lewis lung carcinoma and ovarian cancer models." (PMID 28804221, 2017). "Also median difference between peritoneal fluid and serum concentrations of TNF-alpha was the highest in ovarian cancer patients, followed by women with endometrioma and serous ovarian cysts." (PMID 28376925, 2017). "Also median concentrations of TNF-alpha in peritoneal fluid were the highest in ovarian cancer patients, followed by women with endometrioma and those with benign serous cysts." (PMID 28376925, 2017). "Finally, miR-199a-5p was also demonstrated to target IkappaB kinase-beta in ovarian cancer cells, resulting in increased sensitivity to TNF-α-induced apoptosis following forced expression of miR-199a-5p." (PMID 26717044, 2016). "Similarly, the levels of various cytokines TNF-α and IL-1α were also increased in the patients of ovarian cancer (32.17±3.52 pg/ml and 7.04±0.85 pg/ml respectively)." (PMID 27902750, 2016). "Furthermore, released pro-inflammatory cytokines such as TNFα contribute to increased migration and invasiveness of breast and ovarian cancer cells." (PMID 27608835, 2016).
ovarian carcinoma (continued). "The aim of this study was to identify critical regulators in the signaling pathways of the TNF network in ovarian cancer cells that might be therapeutic targets." (PMID 26871292, 2016). "Stress variables (MDA, AGEs, AOPPs, NO), profile of antioxidants (SOD, Catalase, Vitamin E & A, GSH, GRx, GPx) and inflammatory biomarkers (MMP-9, MMP-2, MMP-11, IL-1α and TNF-α) were biochemically assessed from venous blood of fifty ovarian cancer patients and twenty healthy control subjects." (PMID 27902750, 2016). "The aim of the current study was to determine whether there are differences in immunohistochemical tissue staining of cytokine tumor necrosis factor-α (TNF-α) and interleukin-10 (IL-10) between benign tumors and malignant primary ovarian cancer." (PMID 25624918, 2015). "We selected ovarian cancer cell lines OVCAR-3, SKOV-3, CaOV-3 and TOV-21G to determine PCR arrays containing genes that encode human chemokines and chemokine receptors after the addition of EGF or TNF." (PMID 23800251, 2013). "Thus blockage of the TNF network using neutralizing antibodies or siRNA reduces the ovarian cancer burden." (PMID 23800251, 2013). "Thus the present study was designed to assess the characteristics of the chemokine profiles elicited by EGF and TNF, and determine if they induce any synergistic effects with respect to key chemokines in ovarian cancer cell lines." (PMID 23800251, 2013). "As the cancer cells tested do not express CXCL13 (a ligand for CXCR5), the novel role of CXCR5 in ovarian cancer cells in response to EGF or TNF may highlight their interaction with immune cells expressing CXCL13 in the tumor microenvironment." (PMID 23800251, 2013). "Targeting these proinflammatory chemokines may be a promising therapeutic strategy for ovarian cancer with abundant TNF and EGFR activation patterns." (PMID 23800251, 2013). "Since the condition medium from TWEAK stimulated THP-1 cells should contain both TWEAK and TNF-α, we proposed that this condition medium might be able to inhibit ovarian cancer cell proliferation." (PMID 23469193, 2013). "Targeting these proinflammatory chemokines may support a promising therapeutic strategy for inflammatory ovarian cancer with abundant TNF and EGFR activation pathways." (PMID 23800251, 2013). "Interestingly, saxatilin, a snake venom shown to inhibit TNF-induced proliferation in ovarian cancer cells, was found to block the TNF effect by suppressing CXCL8 expression." (PMID 24376747, 2013). "Based on the synergistic increase of CCL20 and CXCL8 in response to EGF and TNF, CCL20 and CXCL8 may be the dominant chemokines found in ovarian cancer cells with abundant TNF, and/or activation of the EGFR." (PMID 23800251, 2013). "Both IL-1β and TNF has been shown to regulate ovarian cancer in nude mouse xenograft models." (PMID 22296757, 2012). "TNF is a proinflammatory cytokine abundantly expressed in ovarian cancer." (PMID 23300534, 2012). "To assess whether Themis2 was necessary for LPS-induced TNF production in primary human macrophages we used two siRNAs previously shown to inhibit Themis2 mRNA expression in a human ovarian cancer cell line." (PMID 20644716, 2010). "However, the results of first trials to treat breast or ovarian cancer with TNFα inhibitors have been, so far, inconclusive." (PMID 20064207, 2010). "Nuclear proteins from 2008 ovarian cancer cell line treated with TNF-α were able to shift (bind) oligonucleotide sequences containing the predicted NF-κB binding site of human PIK3CA promoter, but were not able to shift either mutant or mock oligonucleotide sequences." (PMID 18335034, 2008). "Interestingly, studies on the levels of TNF-α using either RNA in-situ hybridization of tissue arrays or semi-quantitative reverse polymerase chain reaction of mRNA in ovarian cancer have shown that TNF-α expression was present at higher levels in ovarian carcinoma compared to normal tissues." (PMID 36899361, 2023).
ovarian carcinoma (continued). "Similarly, elevated ovarian TNF-α contributes to tumor angiogenesis and ovarian cancers." (PMID 35881588, 2022). "Nonetheless, increased serum levels of CRP and TNF-α have been detected in women as early as 5 years prior to the time of ovarian cancer diagnosis, although there is uncertainty as to whether these markers are reflective of local site inflammation pertinent to the ovarian tumor microenvironment." (PMID 35740687, 2022). "Moreover, we further performed a cytokine array analysis, and HM‐macrophages coculture caused a significant increase in many inflammatory cytokines (G‐CSF, GM‐CSF, sICAM1, IL‐α, IL‐1β, IL‐1RA, IL‐6, CCL3, and TNFα), which are known to be abundantly present in ovarian cancer ascites." (PMID 35403834, 2022). "Moreover, to our knowledge, we are the first to determine the cutoff level of IL-8 and TNF-α in the serum that could be used in diagnosis of ovarian cancer." (PMID 34573967, 2021). "Hence, this study aimed to investigate whether IL-6, IL-8, and TNF-α could be considered as new useful markers for diagnosis of ovarian cancer." (PMID 34573967, 2021). "Besides, PDCD6 could mediate the pro-apoptotic activity of cisplatin or TNFα through the downregulation of NF-κB expression in human ovarian carcinoma cells." (PMID 32597292, 2020). "Thus, we hypothesized that C. militaris induced TNF-α/TNFR signal transduction pathway-mediated apoptosis of ovarian cancer cells." (PMID 32020859, 2020). "Similarly, TNFα upregulated MCP-1 on human ovarian cancer IGROV1 cells (right)." (PMID 33203088, 2020). "Furthermore, in vivo experiments showed that INH14 decreased TNFα formed after lipopeptide‐induced inflammation, and treatment of ovarian cancer cells with INH14 led to a reduction of NF‐kB constitutive activity and a reduction in the wound‐closing ability of these cells." (PMID 30447158, 2019). "The ovarian cancer ascites used in our study from patients in advanced disease stages showed a mixture and levels of soluble factors similar to previous studies, with a predominance toward Th2 vs Th1 type cytokines, and high levels of IL-6 and TNF compared to serum." (PMID 29163543, 2017). "In addition, Jianping Liu and his colleagues found that the overexpression of ADAMTSL4 could facilitate the tumor necrosis factor (TNF) induced OV-90 cells (ovarian cancer cells) apoptosis." (PMID 28107202, 2017). "Additionally, it has recently been identified that the critical soluble mediators of type-1 immune effector cells, IFNγ and TNFα, synergize in the induction of COX-2, the key enzyme in PGE2 synthesis, implicated in hyperactivation of MDSC within the TME of ovarian cancer patients." (PMID 28536377, 2016). "The vertebrate gene icb-1 previously has been shown to inhibit growth of ovarian cancer cells in vitro and to suppress expression of ovarian cancer biomarkers like kallikrein-related peptidase 10 and claudin 16 or other cancer-related genes activated by estrogens or TNFα." (PMID 24826199, 2014). "Their efficacy was tested in 3D collagen models of ovarian cancer, using SKOV3 and OVCAR8 cell lines, activated by tumor necrosis factor-alpha (TNFα) and lysophosphatidic acid (LPA)." (PMID 41897313, 2026). "In breast and ovarian cancers, the TNF-α secreted by malignant cells potently induces CCL2/MCP-1 expression, with nearly a twofold increase upon TNF-α stimulation compared with its inhibition." (PMID 41341593, 2025). "RT−qPCR revealed that transcription levels of pro-inflammatory cytokines including IL-8, TNF−α, IFN−α, IFN−β and IFN−γ were significantly elevated by 50–300-fold in oncoVV-shHSP70−treated ovarian cancer cell lines compared to controls." (PMID 41305448, 2025). "A retrospective analysis of patients undergoing radical ovarian cancer surgery revealed that, compared to the Midazolam group, the DEX group had stable hemodynamics, reduced the expression of TNF-α and IL-6, and suppressed perioperative stress responses." (PMID 40309242, 2025).
ovarian carcinoma (continued). "We found that the activation of NF-κB signaling by tumor necrosis factor (TNF)-α, a cytokine found in ovarian cancer tumors and ascites, enhanced the secretion of HE4 while its inhibition suppressed HE4 levels." (PMID 39621651, 2024). "TAMs also affect iron storage and release, secrete cytokines such as IL-6, tumor necrosis factor-α (TNF-α), and interferon-γ (IFN-γ) that regulate iron metabolism, and enhance the invasiveness of ovarian cancer cells." (PMID 39061859, 2024). "FC2 was shown to modulate the NF-κB pathway and induce cancer cell death in two human breast adenocarcinomas and in ovarian carcinoma cell lines, both as a single agent and in combination with known IAP antagonists or with the cytokine TNF." (PMID 36615638, 2023). "Olaparib maintenance treatment can significantly decrease the IL‐6 and TNF‐α level, and increase IFN‐γ level and the CD4+/CD8+ ratio in patients with recurrent ovarian cancer." (PMID 37904699, 2023). "TNF-α belongs to the TNF/TNFR cytokine superfamily, which is commonly detected in biopsies of human cancers (such as epithelial tumors, ovarian cancer, and renal cancer)." (PMID 37817484, 2023). "The role of interleukin‐6 (IL‐6), tumor necrosis factor‐α (TNF‐α), and IFN‐γ in the development of ovarian cancer has attracted much attention." (PMID 37904699, 2023). "In human ovarian cancer, LAG-3+PD-1+CD8+T cells were more dysfunctional in IFN-γ and TNF-α production compared with LAG-3+PD-1- or LAG-3-PD-1-CD8+subsets." (PMID 35992809, 2022). "Reports show that the CK2α knockdown or inhibition of CK2 (CX-4945) can significantly reduce the release of TNF, IL-6 and VEGF cytokines in ovarian cancer cells by suppressing the JAK/STAT3 and NOTCH signal pathway." (PMID 36530985, 2022). "Further studies are needed to better understand the specific pathway and mechanisms involved in the increase in ectopic ovarian cancer growth and protein levels of CB2 and TNFα following chronic administration of CB2 (JWH-133) agonist." (PMID 35242036, 2022). "Ovarian cancer patients have been found to have a higher concentration of inflammatory cytokines such as IL-6, CCL2/MCP-1, and TNF-α, which play an important role in the disease’s genesis and progression." (PMID 36386196, 2022). "Elevated TNF-α level was reported in the follicular fluid of obese-PCOS women and was suggested to be the link between PCOS with ovarian cancers." (PMID 35881588, 2022). "We will then evaluate and determine the mechanisms involved in ovarian cancer tumor growth by measuring levels of anandamide and 2-arachidonoyl glycerol as well as protein levels of CB1, CB2, ERα, ERβ, GPER, TNFα, IL-1β and IL-6 in ovarian and tumor tissues." (PMID 35242036, 2022). "At this regard, in 1998 we had demonstrated that high levels of pro-inflammatory cytokines such as IL-6, tumor necrosis factor (TNF)-α, IL-1, and CRP are correlated with impaired T-cell responses in women with advanced epithelial ovarian cancer." (PMID 33550983, 2021). "In this study, we attempted to evaluate the effects of CME to promote TNF-α/TNFR-mediated signaling and apoptosis induction in human ovarian cancer cells." (PMID 32020859, 2020). "The results of the HOUP hub genes confirmed that the expression levels of TNF, ESR1, CDK1, CXCR4 and MUC1, indicating these 5 hypomethylated genes were activated in ovarian cancer development." (PMID 32192517, 2020). "The expression of pro-inflammatory factors, such as IL-1, IL-6, TNF-α and COX-2, dues to the histological heterogeneity of ovarian cancers." (PMID 31088412, 2019). "HM-1 and ID8 mouse ovarian cancer cells expressed very low levels of VISTA, and the expression did not increase following treatment with IFN-γ, IL-4, IL-6, IL-10, IL-17, or TNF-α." (PMID 30382166, 2019). "Mechanistic studies revealed that the secretion of TNF-alpha after ovarian cancer cells were treated with APG-1387 and found that the secretion of TNF-alpha was in time-dependent manner." (PMID 29530056, 2018).
ovarian carcinoma (continued). "In ovarian cancer, pDC induced IL-10 secreting CD4+ and CD8+ Tregs and enhanced angiogenesis, mediated by the secretion of TNF-α and IL-8." (PMID 30200478, 2018). "In this study, we used inflammatory mediator, TNF-α, which has been shown to participate in both the initiation and progression of cancer, and demonstrated that CCL5 is highly expressed in an ovarian cancer cell line under these conditions." (PMID 29844932, 2018). "ALT-803 also enhanced the cytotoxic function (as measured by increases in CD107a, IFN-γ, and TNF-α) of NK cells from PBMC or ascites, when coincubated with ovarian-cancer cell lines." (PMID 30200478, 2018). "In this study we found that TNFα, IFNγ and MUC16 are often strongly co-expressed in endometrial, breast and ovarian cancers with cytokine staining intensity positively correlating with MUC16 staining in breast and ovarian cancers, in particular." (PMID 26918940, 2016). "It was reported that an autocrine inflammatory cytokine network of inflammatory cytokine TNF-α, angiogenic factor VEGF, and chemokine CXCL12 existed in ovarian cancer microenvironment and stimulated tumor neoangiogenesis." (PMID 25887589, 2015). "Ovarian cancer SKOV3 cells were treated with TGF-β1 (0, 10, 20, 30 ng/mL), TNF-α (0, 10, 20, 30 ng/mL) or interleukin-1β (0, 10, 20, 30 ng/mL) for 48 hours." (PMID 25895127, 2015). "C4-27z and C4opt-27z CAR T cells exclusively recognized FRα+ ovarian cancer lines, secreting high levels of Th-1 cytokines, including IFN-γ, IL-2, TNF-α and MIP-1A." (PMID 26359629, 2015). "Transforming growth factor (TGF)-β1, tumor necrosis factor-alpha (TNF-α) and Interleukin-1β are expressed in ovarian cancer, which can promote ovarian tumorigenesis through an inflammatory response." (PMID 25895127, 2015). "Our results indicated that TGF-β1, TNF-α, and interleukin-1β regulated MARCH7 expression to promote tumor metastasis of ovarian cancer." (PMID 25895127, 2015). "CPE treatment of ovarian cancer cells affects TJ function, and treatment with recombinant CPE fused to tumor necrosis factor has cytotoxic effects in ovarian cancer cells, supporting the possible development of CPE as targeted therapy for ovarian cancer." (PMID 24009024, 2013). "Our results indicate that ovarian cancer cells induce CCL20, CXCL1-3 and CXCL8 as the primary chemokines in response to EGF or TNF." (PMID 23800251, 2013). "In our previous study, inflammatory agents including bacterial endotoxin lipopolysaccharide (LPS) and proinflammatory cytokines interleukin-1 (IL-1) and TNF, induced CXCL1-3 and CXCL8 in ovarian cancer cells by involving NF-κB signaling." (PMID 23800251, 2013). "One of the primary findings in this study is that in these four ovarian cancer cell lines, CCL20, CXCL1-3 and CXCL8 were the major chemokines that responded to EGF or TNF by involving NF-κB, Akt and Erk signaling pathways." (PMID 23800251, 2013). "The chemokine network revealed that ovarian cancer cells commonly expressed high levels of proinflammatory chemokines such as CCL20, CXCL1-3 and CXCL8 in response to EGF or TNF." (PMID 23800251, 2013). "In vitro, we demonstrated that TWEAK only inhibited ovarian cancer HO-8910PM cell proliferation in combination with tumor necrosis factor-α (TNF-α), whereas either TWEAK or TNF-α alone didn’t affect HO-8910PM cell growth." (PMID 23469193, 2013). "Particularly, tumor necrosis factor (TNF), abundantly expressed in ovarian cancer, enhanced cell proliferation by decreasing the G0-G1 phase in CXCR2 transfected cells." (PMID 24376747, 2013). "We used intraperitoneal xenografts of the human ovarian cancer cell line IGROV1-Luc in Balb/c nude mice, chosen because it was previously reported that growth of these xenografts is inhibited by knock-down of TNF-α." (PMID 22792380, 2012).